CASP1 (caspase 1)
Diseases named in the same sentence as CASP1 in open-access papers (continued):
Sharing a sentence is not in itself a finding about the gene and the disease.
Sepsis (continued). "Similarly, the increase in gasdermin expression in different tissues during sepsis was also dependent on caspase-1 and -11." (PMID 34996441, 2022). "In addition, caspase-1 has been proven to be a key actuator of inflammation, pyroptosis, and sepsis." (PMID 35847986, 2022). "In 2019, a study showed that Dexmedetomidine could reduce pyroptosis and histone release of astrocytes by reducing NLRP3 and caspase-1 recruitment in vivo and vitro, which might protect comprehensively nerve cells from damage in sepsis." (PMID 35572571, 2022). "Also, we did not observe significant changes in IL-1β and IL-18 levels between wild-type and Casp1−/− mice administered a high dose of HNP-1 after sepsis onset." (PMID 35935811, 2022). "Additionally, NLRP3-dependent caspase-1/11-GSDMD pathway was previously demonstrated to mediate pyroptosis in the hippocampus of a sepsis model." (PMID 35508474, 2022). "In animal models of sepsis-induced AKI, the expression levels of NLRP3, apoptosis-associated speck-like protein containing a CARD, and caspase-1 were upregulated, and renal injury was ameliorated by NLRP3 deficiency or caspase-1 inhibition." (PMID 35359999, 2022). "In human studies using plasma specimens from critically ill patients, the expression of inflammasome-related caspase 1, IL-18 and IL-1β mRNA transcripts was significantly higher in patients with sepsis or ARDS, compared with patients with systemic inflammatory response syndrome alone." (PMID 36232959, 2022). "Experimental sepsis evoked a robust increase in the assembly of the NLRP3 complex in liver and kidney, which was associated with a subsequent increase in the cleavage of caspase-1, when compared to animals in the Sham group." (PMID 35178052, 2022). "Thus, the intraperitoneal administration of a high dose of HNP-1 induces liver endothelial NLRP3/caspase-1 inflammasome activation and subsequently destroys cell junctions, thereby increasing vascular permeability after sepsis onset." (PMID 35935811, 2022). "Moreover, genetic deficiency of nucleotide-binding oligomerization domain-like receptor protein-3 or caspase-1 abrogated the high mortality and disrupted liver interendothelial junctions caused by high dose of HNP-1 during sepsis." (PMID 35935811, 2022). "In sepsis, the main proteins in neutrophil pyroptosis (caspase-1/11, GSDMD) play a crucial role." (PMID 36059483, 2022). "In contrast, genetic depletion of core components of inflammasomes, such as Nlrp3, Casp1, Casp11, and gasdermin D (Gsdmd), protects against septic shock or lethal endotoxemia in mice, turning them into a promising target for treatment of sepsis." (PMID 33796108, 2021). "Important to mention is that caspase-1 positive EVs were also detected in critically ill, non-septic patients, but the EV-associated caspase-1 activity was higher in sepsis patients." (PMID 34451925, 2021). "The effects of HSPCs-targeted inhibition of caspase-1 and -3 in sepsis await characterization." (PMID 34367170, 2021). "Animal death caused by sepsis in response to intravenous injection of PAMP from E. coli was attenuated in mice with Casp1, Casp1/11, and Gsdmd depletion but not in Tlr4–/–, Casp11–/– mice or mice lacking receptors for IL-1B (Il1r–/–) and IL-18 (Il18r–/–)." (PMID 34858408, 2021). "Blockade of the CitH3-Caspase-1 pathway may represent a promising therapeutic target for septic shock and sepsis-induced ALI." (PMID 34950139, 2021). "Moreover, in our in vivo study, the silence of TXNIP markedly decreased the expression level of NLRP3/caspase-1 pathway-related genes and alleviated the damage of the kidney under the sepsis conditions, which is similar with the result of miR-30c-5p treatment." (PMID 32892306, 2021). "In accordance with the expected results, we observed a significant increase in the expression levels of pyroptosis-related markers in the liver of CD38-deficient septicemia mice, such as NLRP3, cleaved caspase-1, IL-1β, and IL-18, accompanied by the increase in cleaved caspase-3." (PMID 33860064, 2021).
Sepsis (continued). "The assembly of the P2X7R-NLRP3-caspase-1 complex plays a key role in the induction/progression of rheumatoid arthritis, Crohn’s disease, liver fibrosis, sepsis, renal inflammation, pulmonary inflammation, and the amplification of neurodegenerative or mood diseases." (PMID 35008658, 2021). "While Caspase-1–mediated pyroptosis plays an important role in chronic autoimmune and other inflammatory diseases, Caspase-11–dependent noncanonical pyroptosis exacerbates pathologies in mouse models of sepsis." (PMID 33055424, 2020). "Caspase-1-dependent pyroptosis plays an important role in the occurrence and development of sepsis." (PMID 32258157, 2020). "Numerous studies have demonstrated that specific inhibition of caspase-1 could decrease the bacterial load and inflammation and is beneficial to survival in mouse models of sepsis." (PMID 32258157, 2020). "The results showed that sepsis resulted in upregulated liver caspase-1/11 expression." (PMID 32295272, 2020). "However, little work has been devoted to the role of ASC, the upstream process of caspase-1, in sepsis." (PMID 33613537, 2020). "Therefore, the activation of caspase-1 and the resultant pyroptosis plays a significant part in sepsis pathogenesis and mortality." (PMID 32825174, 2020). "Therefore, by monitoring the changes in NLRP3 and caspase-1, we observed pyroptosis of cortical neurons in rats with sepsis-induced brain injury after different treatments." (PMID 31775794, 2019). "This increase in expression was reduced by MRS/MRM treatment, indicating that methane could inhibit the NLRP3/caspase-1/IL-1β signaling pathway to decrease pyroptosis offering a protective effect during sepsis." (PMID 30779706, 2019). "Finally, MRS suppressed the activation of the NLRP3/Caspase-1/IL-1β inflammasome signaling pathway to alleviate the tissue and cell damage induced by sepsis." (PMID 30779706, 2019). "Deficient autophagy was associated with increased NLRP3 inflammasome assembly and culminated caspase-1 activation as observed in sepsis, enabling enhanced cleavage of pro-IL-1β and pro-IL-18 into their biologically active forms IL-1β and IL-18 in DSS-treated UVRAGFS mice colons." (PMID 31831743, 2019). "Peripheral blood transcriptomics in humans have shown a parallel scenario since particular key mediators of the initial neutrophil response to infection, such as LCN2, BPI, CD24, CASP1 and MMP8, were strongly dysregulated in patients with sepsis-associated ARDS compared to sepsis patients." (PMID 31426444, 2019). "To explore whether MRS could affect the NLRP3 inflammasome signaling pathway to improve sepsis injury, we measured the expression levels of p-P65, P65, pro-caspase-1, pro-IL-1β and NLRP3/caspase-1/IL-1β by Western blotting 12 and 24 h after CLP." (PMID 30779706, 2019). "Finally, this study only explored caspase-1-dependent pyroptosis, but we still need further study to elucidate the mechanism of other caspases (caspase-4/5/11) activating pyroptosis in sepsis." (PMID 31775794, 2019). "In summary, this present works provides evidence that caspase-1 plays a crucial role in regulating apoptosis of pulmonary vascular endothelial cells, which may have particular relevance for sepsis-related vascular injury." (PMID 26710067, 2015). "We hypothesized that MVs may serve to package and deliver active caspase-1 and other inflammasome components during human sepsis thereby contributing to the lymphocyte apoptosis characteristic of sepsis." (PMID 24643116, 2014). "Our work implicates caspase-1 as one of the potential apoptotic signaling factors during sepsis." (PMID 24643116, 2014). "To assess whether the NLRP3 inflammasome/caspase-1 pathway would be activated in a polymicrobial model of sepsis we used the FIP model." (PMID 25216263, 2014). "The fact that caspase-1 circulates in MVs during sepsis is also novel." (PMID 24643116, 2014).
Sepsis (continued). "Hence, the caspase-1 function in sepsis was independentof processing and releasing IL-1β and IL-18, in spite of having reducedlevels of serum IL-1β, IL-18 and IL-6 incaspase-1−/− mice during sepsis." (PMID 25412304, 2014). "Of importance, caspase-1 knockout exhibits the protective effect on a murine sepsis model, where the plasma IL-1β level was completely depressed, suggesting a crucial role of caspase-1 in sepsis." (PMID 24454930, 2014). "The NLRP3 inflammasome is an intracellular multi-protein complex that triggers caspase-1 mediated maturation of interleukin-1β (IL-1β); one of the most potent mediators of inflammation and a major cytokine produced during severe infections, like sepsis." (PMID 25400921, 2014). "Additionally, our in vitro work showed that this effect is blocked by inhibition of caspase-1, further implicating caspase-1 as a signal of sepsis-induced apoptosis and confirming previous observations by multiple investigators in animal models." (PMID 24643116, 2014). "The precise role of caspase-1 in human sepsis remains to be elucidated." (PMID 24643116, 2014). "Importantly, the knock-down of caspase-1 gene reduced splenic cell death in an E. coli induced-sepsis model and HMGB-1 release in an LPS induced-endotoxemia model, and improved the survival rates in both models." (PMID 24454930, 2014). "However, the mechanism by which caspase-1 induces lymphocyte apoptosis in the context of sepsis remains poorly understood." (PMID 24643116, 2014). "Furthermore, in patients with sepsis, caspase-1 levels are significantly decreased, and the inhibition of caspase-1 and defective IL-1β production constitute an important immunological feature of sepsis." (PMID 24098117, 2013). "Inflammasome activation is exclusively responsible for caspase-1-mediated IL-1β and IL-18 maturation and secretion in immune cells, and circulating IL-1β and IL-18 levels are known to be increased in critically ill patients with both sepsis and ARDS." (PMID 24391478, 2013). "This study documenting decreased activation of caspase-1 and inhibited cytokine responses in septic patients and in volunteers exposed to intravenous endotoxin provides new insights into the mechanism of cytokine down-regulation in sepsis patients." (PMID 21244670, 2011). "We found that caspase-1 activation was decreased in sepsis and after endotoxin challenge." (PMID 21244670, 2011). "Since sepsis in this series of patients was mainly caused by Gram-negative bacteria, we also investigated caspase-1 activity in volunteers injected intravenously with LPS." (PMID 21244670, 2011). "Nevertheless, caspase-1 clearly can contribute to cell death as has been described for macrophages responding to intracellular pathogens in pyroptosis and as we have shown for splenic B lymphocyte apoptosis in response to sepsis." (PMID 19779610, 2009). "However, anti-IL-1β therapy has proved to be ineffective in sepsis trials, and inhibition of caspase-1 has been suggested as potentially rendering individuals more susceptible to infections and severe sepsis." (PMID 19740426, 2009). "Moreover, no data is available in the NTDB about sepsis onset timing, time to antibiotic initiation, fluid resuscitation, adherence to sepsis protocols and key biomarkers (lactate, procalcitonin, CRP, caspase-1) which are essential for adequate sepsis management." (PMID 40901518, 2025). "Hence, it is plausible to speculate that NLRC4 may induce cell death through caspase-1 activation and enhancement of the inflammatory response, ultimately contributing to the onset of sepsis." (PMID 40028203, 2025). "Furthermore, we observed that when exogenous HNP-1 was intraperitoneally administered into Nlrp3−/− and Casp1−/− mice 6 hours after sepsis, the survival of mice administered a high dose of HNP-1 was comparable to that of mice administered a low dose of HNP-1 or PBS." (PMID 35935811, 2022).
Sepsis (continued). "Studies have shown that caspase-1 can cleave several key enzymes in glycolysis, including aldolase, triose-phosphate isomerase, glyceraldehyde-3-phosphate dehydrogenase, alpha-enolase, and pyruvate kinase, which are further involved in the occurrence of sepsis and septic shock." (PMID 35847986, 2022). "In addition, transgenic expression of CASP4 in Casp1−/−/11−/− mice renders increased susceptibility to LPS-induced shock, indicating the pathogenetic role of human non-canonical inflammasome in sepsis." (PMID 33796108, 2021). "In this study, we demonstrated that caspase-1-inhibitor AC-YVAD-CMK could significantly alleviated sepsis-induced acute kidney injury, with decreased histological injury in renal tissues, suppresses the accumulation of neutrophils and macrophages in renal tissues, and decreased sCR and BUN level." (PMID 34222479, 2021). "Thus, suppression of CASP-1 activity can attenuate DC pyroptosis secondary to sepsis." (PMID 34741186, 2021). "Therefore, targeting human caspase-4 and caspase-5 (caspase 11 in mouse) may be more effective than inhibiting caspase-1 in patients with sepsis." (PMID 34858408, 2021). "In addition, caspase-1-mediated pyroptosis of immune cells may lead to immune paralysis in the final stage of sepsis." (PMID 33324236, 2020). "This cell death function of caspase-1 has been described for macrophages responding to intracellular pathogens in pyroptosis and as we have shown for splenic B lymphocyte apoptosis in response to sepsis and smooth muscle cell apoptosis in a model of atherosclerosis." (PMID 24643116, 2014). "The aim of the present study is to evaluate whether sepsis activates NLRP3 inflammasome/caspase-1/IL-1β pathway in cardiac fibroblasts (CFs) and whether this cytokine can subsequently impact the function of cardiomyocytes (cardiac fibroblast-myocyte cross-talk)." (PMID 25216263, 2014). "We adjusted our model to control for this increased severity of illness, and still found a significant relationship between sepsis and elevated MV encapsulated caspase-1, but there is still the possibility that caspase-1 may play less of a role in less severely ill septic patients." (PMID 24643116, 2014). "Our previous work has shown that caspase-1 does not kill native peripheral blood monocytes or macrophages and that lymphocytes are particularly susceptible to sepsis-induced apoptosis compared with other tissues, thus supporting the likelihood of lymphocyte specific targeting." (PMID 24643116, 2014). "On the other hand, caspase-1 activation of IL-1β and IL-18 also represents protective host defense mechanisms, and their inactivation may well be an important component of immunoparalysis in sepsis." (PMID 21244670, 2011). "Although caspase-1 is generally categorized as an “inflammatory” caspase by virtue of its activation of IL-1β and IL-18, it is now clear that caspase-1 also plays a role in certain forms of cell death, e.g. sepsis induced lymphocyte apoptosis and bacterial induced pyroptosis." (PMID 19779610, 2009). "In our model, CLP-induced sepsis increased the renal expression of NLRP3, caspase-1 in its mature and activated form, and IL-1β, consistent with previous reports." (PMID 40869248, 2025). "In line with findings for TLR4, MyD88, and NF-κB, sepsis significantly increased renal expression of NLRP3 and caspase-1 and its activated form (cleaved caspase-1 protein) compared to controls, as shown through Western blotting." (PMID 40869248, 2025). "These targets, including ADAM17, CD81, CASP1, and MGMT, lay the foundation for further research into the mechanisms of action of Calculus Bovis in sepsis treatment." (PMID 40258762, 2025). "Remarkably, NF-κB, NLRP-3, Caspase-1, and GSDMD C-NT revealed considerable dose-dependent expression downregulation in response to CLM indicating its anti-pyroptotic effect during sepsis-induced liver dysfunction." (PMID 40770673, 2025).
Sepsis (continued). "In sepsis, sustained or dysregulated activation of the NLRC4–caspase-1 axis can contribute to excessive pyroptosis, systemic inflammation, and multiorgan failure." (PMID 40558557, 2025). "The average values of the four cell death markers (caspase-1, caspase-3, MLKL and p62) two cytokines (IL-1-beta and IFN-gamma) and two MHCs (MHC I-A and MHC II-DRB1) of C19wSepsis, C19NoSepsis and Sepsis alone differed markedly from those of controls." (PMID 40051620, 2025). "In a related study on sepsis induced by lipopolysaccharides (LPS), treatment with CAP was found to increase protein levels of caspase-1, ASC, and NLRP3, as well as the number of PI-positive cells, indicating activation of pyroptosis and apoptosis." (PMID 41226458, 2025). "Specific inhibition of caspase-1 reduces NLRP1 inflammasome expression, and suppresses sepsis, inflammatory cytokine secretion and leukocyte aggregation in septic shock mouse models." (PMID 40153575, 2025). "In sepsis, overexpressed YTHDF1 inhibits CLP‐induced inflammation in mice by upregulating E1 Ub protein ligase 1 to promote NLRP3 ubiquitination and inhibit caspase 1‐dependent pyroptosis, thereby alleviating sepsis." (PMID 40919129, 2025). "Recent studies have shown that in a mouse model of sepsis induced by cecal ligation and puncture (CLP), caspase-1 inhibitors effectively reduced cell death, decreased the release of inflammatory molecules, and preserved the brain’s ultrastructure." (PMID 40458798, 2025). "Furthermore, caspase-1 mediated immune cell pyroptosis may lead to immune paralysis in sepsis." (PMID 39364223, 2024). "The results showed that sepsis significantly promoted NLRP3, Pro Caspase-1, ASC and IL-18 mRNA levels, increased NLRP3, Pro Caspase-1, Cleaved Caspase-1 and ASC protein expression, whereas pretreatment with 6 and 30 mg/kg taraxerone attenuated these effects." (PMID 39543653, 2024). "The results demonstrated that PBMCs from the sepsis group had significantly higher relative protein levels of NLRP3, caspase-1, cleaved GSDMD, and IL-1β than those from the control groups." (PMID 38169584, 2024). "In the sepsis mouse model, the activation of the PERK/ATF4/CHOP signaling pathway trigger NLRP3/caspase-1-mediated pyroptosis and the generation of pro-inflammatory cytokines, leading to elevated mortality rates among septic mice." (PMID 38434710, 2024). "In the context of sepsis, NLRP3 functions by recruiting and activating caspase-1, leading to release of IL-1β and IL-18, initiating a cascade of inflammatory reactions that ultimately leads to substantial inflammation-induced damage and multi-organ failure." (PMID 39364223, 2024). "Evidence beyond our work on caspase-1 and Aβ in ICU-sepsis patients further suggest a complex regulatory relationship between the two." (PMID 38410714, 2024). "During infection and sepsis, the NLRP3-inflammasome initiates pro-caspase-1 activation via auto-proteolysis." (PMID 38410714, 2024). "These limitations notwithstanding, our findings have established a novel relationship between caspase-1 and Aβx-40 that may be important in regulating the short-term host inflammatory response to infection as well as the long-term outcomes in patients hospitalised with sepsis." (PMID 38410714, 2024). "In contrast, the frequencies of active caspase-1-expressing cells were comparable between monocytes and neutrophils after LPS treatment, suggesting that pyroptosis could not explain the selective disappearance of monocytes in peripheral organs after sepsis induction." (PMID 39040105, 2024). "The caspase-1 inhibitor VX765 inhibited caspase-1, suppressed the expression of GSDMD and its cleavage form GSDMD-NT, reduced the pyroptosis and sepsis-induced impairment of the blood–brain barrier and structural damage in the brain." (PMID 37891821, 2023). "ALA reduced the level of NETs, pyroptosis-related proteins (Cl-caspase-1, Cl-GSDMD, ASC), and IL-1β in the lung tissue of sepsis mice." (PMID 37051243, 2023).